TNF (tumor necrosis factor)
Diseases named in the same sentence as TNF in open-access papers (continued):
Sharing a sentence is not in itself a finding about the gene and the disease.
COVID-19 (continued). "Thus, these interleukin levels cannot be compared to those described by other authors for direct dosing from COVID-19 patients serum (IL-6: 19.55 pg/mL mean; IL-10: 3.66 pg/mL mean; TNF-α: 1.11 pg/mL mean) or vaccinated participants serum (IL-6: 25.94 pg/mL mean; IL-10: 11.08 pg/mL mean)." (PMID 38728294, 2024). "However, those on anti–tumor necrosis factor (TNF) therapy may have lower antibody concentrations after 2 or 3 doses of COVID-19 vaccines, with faster waning of antibodies." (PMID 38349178, 2024). "Severe COVID-19 is characterized by an inflammatory profile that involves initial immune evasion by downregulation of Type I Interferon pathways along with significant upregulation of IL-6, IL-8 and TNF-α in the lungs that coincides with increased NF-κB activity." (PMID 37938797, 2024). "Additionally, TNF itself may exert suppressive effects on specific proinflammatory factors related to COVID-19, such as the expression of type 1 interferon and the differentiation of Th17 cells." (PMID 39459457, 2024). "Therefore, the combination of TLR4 inhibitor and TNF-α neutralizing antibody may represent a promising therapeutic strategy in treating CRS in patients of COVID-19 and other syndromes, such as CAR-T cell anti-tumor therapy, where CRS is a common side effect." (PMID 39359733, 2024). "Further encouraged by the parallel between COVID-19 and CF in terms of activation of both ENaC and TNFα/NFκB signaling, we have hypothesized that inflammation in the COVID-19 airway might be due to inhibition of CFTR signaling in normal lung epithelial cells by the SARS-CoV-2 spike protein." (PMID 39043712, 2024). "However, we observed a substantial increase in IL-6 and CRP levels associated with the severity of COVID-19, while no such trend was observed for IL-1β and TNF-α." (PMID 39188881, 2024). "Furthermore, this study identified that age, BMI, fever duration, leucocyte count, lymphocyte proportion, proportion of CD3+ T cells, TNF-α, and IL-10 were independently associated with occurrence of severe cases in children hospitalized with H1N1 infection during the post-COVID-19 period." (PMID 38566022, 2024). "Recent studies have reported that COVID-19 patients are mostly in a high systemic inflammatory condition with excessive cytokine releases which is characterized by high levels of interleukin-6 (IL-6), IL-8, and tumor necrosis factor-α (TNF-α) that contribute to deadly complications." (PMID 39395941, 2024). "Also, some of the biosignatures including but not limited to TNF, IL10, have been verified using multiplex biosensor techniques to be associated with COVID-19, and as such these biosignatures could serve as markers to monitor the disease development." (PMID 39040605, 2024). "Cytokines such as IL-2, IL-6, TNF-α, IFN-γ, and IL-10 could serve as predictors for early prediction of the severity of COVID-19; hence, this study aimed to evaluate the association of cytokine levels IL-2, IL-6, TNF-α, IFN-γ, and IL-10 with the severity of COVID-19 in Bangladesh." (PMID 38707035, 2024). "Secondly, the systemic inflammatory response syndrome (SIRS) induced by COVID-19 can lead to a cytokine storm, characterized by the release of large quantities of pro-inflammatory cytokines such as interleukin-6 (IL-6), interleukin-1β (IL-1β), and tumor necrosis factor-alpha (TNF-α)." (PMID 38999316, 2024). "Therefore, the identification of more efficacious methods for the suppression of TNF-α production or neutrophil recruitment may facilitate the development of superior therapeutic interventions for the treatment of severe cases of COVID-19." (PMID 39652608, 2024). "However, other studies have found elevated TNF-α levels in severe COVID-19." (PMID 38791465, 2024).
COVID-19 (continued). "The results showed that COVID-19 patients had significantly higher levels of all three cytokines compared to the control group: IL-6 at 165.85 ng/mL (±20.13) vs. 86.68 ng/mL (±17.30); IL-1β at 52.30 ng/mL (±11.71) vs. 6.30 ng/mL (±6.61); and TNF-α at 179.54 ng/mL (±28.92) vs. 18.50 ng/mL (±4.25)." (PMID 39201618, 2024). "Furthermore, COVID-19 can induce the release of cytokines, such as interleukin-1β, interleukin-6, and tumor necrosis factor-α, which may lower serotonin levels by altering its biosynthesis, release, and reuptake." (PMID 38792343, 2024). "Indeed, a cytokine storm had been observed in severely ill COVID-19 patients, and most of these patients exhibited markedly increased serum levels of proinflammatory cytokines, such as interleukin (IL)-6, tumor necrosis factor alpha (TNF-α), GM-CSF, and IL-1β." (PMID 37762435, 2023). "Similarly, another study confirmed that several serum pro-inflammatory mediators including IL-2R, IL-6, IL-10, and TNFα are increased in severe (n = 11) compared to moderate (n = 10) COVID-19 patients, while serum IFNγ levels were decreased negatively correlating with disease severity." (PMID 36941580, 2023). "However, the expression of IL6 and TNF, well-known markers associated with severity in COVID-19, was lower in non-classical monocytes in Yh034 than in Yh002/Yh004, parallel to the clinical status of each patient at the time point." (PMID 36732528, 2023). "Furthermore, blood levels of T-cell-associated cytokines, mainly IFN-γ, TNF-α, IL-2, IL-6 and IL-17, increase during severe COVID-19, as opposed to measurements in controls." (PMID 37568402, 2023). "The role of ∝2-M in COVID-19 has been proposed based on its versatility; specifically, in its tetrameric form, it is able to inhibit all four classes of proteases, while in its dimeric form, it shows increased interaction with mediators of inflammation, such as TNF-∝, Il-2, and IL-6." (PMID 37371071, 2023). "TNF-α could be a promising biomarker for predicting pulmonary complications and may be a potential target for therapeutic intervention in patients with post-COVID-19 complications." (PMID 37445288, 2023). "Based on the results of the in vivo COVID-19 cytokine storm study, we focused on the IL-1β, IL-2, IL-6, TNFα, IL-4, and IL-10 molecular pathways as the key elements of the inflammatory response in order to identify the molecular mechanisms of peptidergic regulation of the cytokine storm in COVID-19." (PMID 37686182, 2023). "Furthermore, and highlighting the translational relevance of our findings, galectin-9 plasma levels have been shown to correlate with elevated cytokines in COVID-19 patients and addition of recombinant galectin-9 induced IL-6 and TNFα secretion in those patients." (PMID 37755527, 2023). "While TNF-α, IL-1β, and IL-6 are the most important cytokines in this damaging process, in the later phase of critical infectious disorders, such as severe COVID-19 patients, the systemic levels of IL-4, IL-10, and IL-13 may also increase." (PMID 36671034, 2023). "First, we studied the profile of different soluble pro-inflammatory cytokines (GM-CSF, TNF-α, IFN-γ, IL-1β, IL-2, IL-6, IL-7, IL-10, IL-17A, IL-21) and chemokines mediating monocyte and neutrophil recruitment (IL8, CCL3), whose exacerbated production is associated with severe COVID-19." (PMID 36675231, 2023). "Since cellular immunity is not routinely determined, these results could help to understand the correlation between humoral and cellular immune responses and could contribute to better management of these immunocompromised patients on anti-TNFα inhibitors in the COVID-19 setting." (PMID 36992175, 2023). "However, in newborns of mothers with COVID-19, elevated concentrations of IL-6 (i.e., M = 143 pg/mL) and TNF-α (i.e., M = 103.41 pg/mL) suggest that the babies were suffering from cytokine storms given dosages of the same molecules in the newborns of healthy mothers." (PMID 36979888, 2023).
COVID-19 (continued). "Importantly, our present study demonstrates that phagocytosis of SARS-CoV-2-infected cells is not immunologically silent but can result in the production of the proinflammatory cytokines IL-6 and TNF, both of which are known to be involved in COVID-19 pathogenesis." (PMID 37253946, 2023). "Another hypothesis for the cardiac involvement in COVID-19 implicates the systemic release of pro-inflammatory cytokines (e.g., IL-1, IL-6, TNF-α, IFN-γ, and MIP) and the subsequent “cytokine storm” as the main culprit with subsequent increased vascular wall permeability and myocardial edema." (PMID 36371548, 2023). "These proteins either act as positive regulators of cell death (HBG1, HBB, HBD, and HBA1) or are involved in the cellular response to tumor necrosis factor (FABP4, GPD1, THBS1, ASS1, and PCK2), suggesting that apoptosis may be an important cause of heart failure in patients with COVID-19." (PMID 38087340, 2023). "Severe forms of COVID-19 are driven by a dysregulated inflammatory reaction, also called “cytokine storm”, characterized by high systemic levels of cytokines, including tumor necrosis factor α (TNFα), interleukine-1 (IL-1), interleukine-6 (IL-6), and interferon γ (IFNγ)." (PMID 37108440, 2023). "Importantly, the combination of serum levels of IL-10, IL-23 and TNF-α were strongly linked with non-survivors in COVID-19 patients." (PMID 37283736, 2023). "Moreover, vitamins D and A, selenium, flavonoids, zinc, and unsaturated fatty acids can alleviate inflammatory response in patients with COVID-19 via inhibiting the activation of nuclear factor kappa-B (NF-κB), hence reducing the production of pro-inflammatory cytokines, such as IL-6 and TNF-α." (PMID 38156008, 2023). "Pregnancies complicated by both COVID-19 and preeclampsia, preeclampsia, and COVID-19 significantly had the highest placental damage on apoptotic, pyroptotic, and necrotic pathways shown from caspase-3, caspase-1, and tumor necrosis factor-alpha expressions in the placenta (P<.05)." (PMID 37362630, 2023). "Interestingly, DNase I could prevent systemic inflammation in some COVID-19 patients, including the reduction of pro-inflammatory cytokines TNF-α and IL-6." (PMID 36864506, 2023). "Besides as a biomarker for the prognosis of severe COVID-19, targeting TNF-α using antibodies or inhibitors might reduce lung inflammation, hence a lower incidence rate of severe COVID-19 and death." (PMID 37047115, 2023). "Previous studies found that thymosin drugs could inhibit the inflammatory/activated state of monocytes in the treatment of COVID-19 by reducing the release of proinflammatory mediators such as TNF-α, IL-6 and IL-8, and promote the generation of anti-inflammatory cytokines such as IL-10." (PMID 37743481, 2023). "This patient did not experience severe inflammation at the time of COVID-19, but our data nevertheless highlight an enhancement of inflammatory cascades (TNF/NF-κB and IL-6/JAK/STAT3) in STAT2 deficiency, both in the basal state and during acute COVID-19, mediated predominantly by neutrophils." (PMID 36976641, 2023). "In COVID-19, cytokine storm actions, which may result from the release of TNF-α, interferon, and interleukins, may give rise to multi-organ damage, acute respiratory distress syndrome, pulmonary complications, or disseminated intravascular coagulation infection." (PMID 36766961, 2023). "In the same conjunction point between COVID-19 and the preeclampsia pathways, the vascular damage, inflammation, and thrombosis lead to ischemia and infarction, which will be followed by increasing synthesis of tumor necrosis factor-alpha (TNF-alpha) related to necrosis." (PMID 37362630, 2023). "The main clinical manifestations of COVID-19 patients are the increase of neutrophils and monocytes in the blood, the decrease of lymphocytes, and the increase of inflammatory cytokines, such as interleukin (IL)-6, IL-8, IL-10 and tumor necrosis factor α (TNF-α)." (PMID 37446049, 2023).
COVID-19 (continued). "Inflammatory markers and pro-inflammatory cytokines, such as CRP, ferritin, IL-1β, IL-8, TNF-α, and MCP1, show a significant increase in their serum concentrations, and the elevated neutrophil-to-lymphocyte ratio is associated with more severe cases of COVID-19 that can lead to death more easily." (PMID 37408184, 2023). "TNF is increased in COVID-19 patients, and high baseline levels may be a predictor of mortality." (PMID 37081046, 2023). "In our study, critical COVID-19 groups also exhibited significant positive correlations of U-CysLT values with several systemic inflammatory markers and parameters, namely with the proinflammatory cytokines IL-6 and TNF-α, with CRP and with total leukocytes, neutrophils, eosinophils and NMR ratio." (PMID 36617343, 2023). "Despite the limited number of COVID-19 patients with fatal outcomes involved in our study, we wondered whether the immunopathogenic process induced by the excessive production of TNF-α mediated by NK cells in SARS-CoV-2 infection could play a role in the fatal outcome." (PMID 37342247, 2023). "Among the IBD treatment modalities, corticosteroids could affect COVID-19 severity (P = .21, OR = 2.51, 95% CI [0.276–10.9]), whereas anti-TNFα antibodies (P < .001, OR = 0) and thiopurines (P = .038, OR = 0.16) were associated with a reduced risk of severe COVID-19." (PMID 39131552, 2023). "Although TNF-α signaling is critically required for activating innate immunity against infectious agents, dysregulation of TNF-α signaling can lead to severe complications, such as cytokine storm, that is importantly associated with deaths in COVID-19 patients." (PMID 37047115, 2023). "COVID-19 is an air-borne disease primarily affecting the respiratory system and inducing a severe inflammatory response, thereby releasing numerous inflammatory mediators such as IL-1, IL-6, and tumor necrosis factor-alpha (TNF-α) leading to cytokine storm which has a detrimental effect." (PMID 36874696, 2023). "Furthermore, COVID-19 caused excessive production of proinflammatory cytokines such as IL-6, IL-2, IL-7, granulocyte-colony stimulating factor (G-CSF), Macrophage Inflammatory Protein-1 Alpha ((MIP-1-α)/CCL3, and TNF-α), termed as cytokine storm." (PMID 37377785, 2023). "Furthermore, observational studies have indicated that TNF therapy may be beneficial for patients with COVID-19." (PMID 37397483, 2023). "In addition, the inflammation and necrotic processes were prominently shown by overexpression of caspase-1 and tumor necrosis factor-alpha (TNF-α), which were significantly high in pregnancies complicated by COVID-19 and pregnancies complicated by preeclampsia." (PMID 37362630, 2023). "According to the previous interim analysis, the number of patients receiving advanced therapy, other than anti-TNFα antibody agents was small; therefore, the risk of COVID-19 severity for patients prescribed such agents could not be examined in detail." (PMID 39131552, 2023). "Interestingly, some of the main exerkines, i.e., cytokines that are released during and after exercise, such as IL-6, IL-8, IL-1ra, or TNF-alpha, are the very same ones that are elevated in COVID-19, raising the possibility that common molecular mechanisms are activated." (PMID 37234053, 2023). "Several inflammatory conditions have been linked with COVID-19, including activation of macrophages, hematological dysfunctions, and cytokinaemia or cytokine storm, defined by upregulation of C-reactive protein (CRP), interleukins (IL), and tumor necrosis factor-alpha (TNF-α)." (PMID 37008057, 2023). "However, patients with severe COVID-19, for example, patients with hypoxic respiratory failure, develop hyperinflammation with the release of pro-inflammatory cytokines, such as interleukin (IL)-1, IL-6, IL-8, or Tumor necrosis factor alpha (TNFα)." (PMID 36678457, 2023).
COVID-19 (continued). "Indeed, IL-6 and TNF-α are pro-inflammatory cytokines involved in the immunopathology of COVID-19; IL-6, in particular, can lead to macrophage activation syndrome and cytokine storm, the most serious complications of COVID-19." (PMID 37520439, 2023). "Inappropriate host immune responses in patients with COVID-19 due to the secretion of proinflammatory cytokines such as IL-1, IL-6, and tumor necrosis factor-α (TNFα) could lead to cytokine storms, organ failure, and severe presentations such as pneumonia and neuropsychiatric symptoms." (PMID 37674935, 2023). "Given that a similar proinflammatory response is also observed in COVID-19, the severe forms of COVID-19 are most likely attributable to the hyperactivation of NF-κβ that regulates the synthesis and release of proinflammatory cytokines, such as TNF-α and IL-6, in severe COVID-19 patients." (PMID 37047115, 2023). "Studies have shown that patients critically ill with COVID-19 have higher serum concentrations of proinflammatory cytokines and chemokines, including granulocyte colony-stimulating factor, monocyte chemoattractant protein-1, TNF-α, IL-6 and IL-1β, than healthy individuals." (PMID 36979888, 2023). "Interestingly, in this study, the analysis of the differential expression of cytokines in the mild and severe COVID-19 patient groups revealed the expression of IL-2, IL-6, TNF-α, and IFN-γ to be significantly decreased in severe cases as compared to mild cases." (PMID 36584119, 2022). "On the other hand, a recent meta-analysis of 35 studies has shown that COVID-19 patients receiving anti-TNF treatment regardless of underlying diseases had a lower risk of hospitalization (OR 0.53; 95% CI 0.42-0.67) and ICU admission or death (pooled OR 0.63; 95% CI 0.41-0.96)." (PMID 35812420, 2022). "Interestingly, obviously elevated IL-2, IL-8, IL-10, TNF-α, and IL-12p70 were observed in symptomatic patients with COVID-19 compared with asymptomatic carriers, which were consistent with the results in that of patients with COVID-19." (PMID 35685940, 2022). "Recent advances in the pathophysiologic understanding of coronavirus disease 2019 (COVID-19) suggests that cytokine release syndrome (CRS) has an association with the severity of disease, which is characterized by increased tumor necrosis factor α (TNF-α), interleukin (IL)-6, IL-2, IL-7, and IL-10." (PMID 35223745, 2022). "It was, however, evidenced that renalase plasma levels measured in COVID-19 patients were significantly decreased compared to that of the control group, and demonstrated a negative correlation with inflammatory cytokines plasma levels, namely, IL-1β, IL-6, and TNF-α." (PMID 36132227, 2022). "Another explanation could be that psoriasis patients are well-treated with anti-inflammatory agents, such as anti-TNF antibodies and other biologics and immunosuppressive agents, and that they are not at a higher risk of severe infection with COVID-19." (PMID 36293117, 2022). "Furthermore, it has a positive correlation with pro-inflammatory cytokines such as IL-6 and tumor necrosis factor-α (TNF-α), suggesting that Gal-9 inhibition could be a potential therapeutic approach in COVID-19 patients." (PMID 35432324, 2022). "Furthermore, they also speculated that excess TNF-α inhibited the formation of GC responses in COVID-19 via blocking Tfh cell differentiation." (PMID 36505489, 2022). "Infection with SARS-CoV-2 leads to COVID-19, the severity of which is partly due to host immune responses, including the release of proinflammatory cytokines, such as interleukin (IL)-6, IL-18 and tumor necrosis factor (TNF), with serious biological and clinical consequences." (PMID 35336907, 2022). "Similarly, COVID-19 significantly upregulates TNF-α alongside other cytokines and chemokines." (PMID 35639261, 2022). "Consequently, anti-TNF medicine is being considered a possible treatment for COVID-19." (PMID 37521843, 2022).